MRPL34 (mitochondrial ribosomal protein L34)
Synonyms: L34mt; MGC2633; MGC24974; bL34m
Tractability: Small molecule: a structure with a bound ligand is known. PROTAC: its protein half-life has been measured.
Gene: Protein-coding gene on chromosome 19 (17,292,609 to 17,306,843, forward strand). Ensembl gene ENSG00000130312.
Subcellular location: Mitochondrion
Subcellular location (Human Protein Atlas): Mitochondria
Pathways (Reactome):
Metabolism of proteins: Mitochondrial ribosome-associated quality control; Mitochondrial translation elongation; Mitochondrial translation initiation; Mitochondrial translation termination
Gene Ontology:
Molecular function: structural constituent of ribosome
Biological process: mitochondrial translation; translation
Cellular component: mitochondrial large ribosomal subunit; mitochondrion; mitochondrial inner membrane; mitochondrial ribosome; ribosome
Genetic constraint (gnomAD): Loss-of-function variants: 11 observed, 8.01 expected, observed/expected ratio (o/e) 1.37, 90% interval 0.84 to 1.9. That is too few expected variants to judge how well the gene tolerates losing a copy. Missense variants: 146 observed, 121.43 expected, observed/expected ratio (o/e) 1.2, 90% interval 1.05 to 1.38. Synonymous variants: 59 observed, 52.03 expected, observed/expected ratio (o/e) 1.13, 90% interval 0.92 to 1.41.
Homologues: Orthologues: chimpanzee MRPL34 (97% identical), macaque MRPL34 (97% identical), guinea pig MRPL34 (76% identical), mouse Mrpl34 (75% identical), rat Mrpl34 (74% identical), pig MRPL34 (72% identical), zebrafish mrpl34 (51% identical), tropical clawed frog mrpl34 (49% identical).
Diseases named in the same sentence as MRPL34 in open-access papers:
MRPL34 is named in the same sentence as 10 diseases in open-access papers, as found by Europe PMC text mining. Sharing a sentence is not in itself a finding about the gene and the disease. The quoted sentences say what the papers report.
dystroglycanopathies (1 paper, 2010). "Interestingly, some dystroglycanopathies are accompanied by eye defects and one might speculate that this involves DG mediated energetic stress that is mimicked in the fly by dual mutations in Dg and mRpL34." (PMID 20463973, 2010).
Parkinson disease (1 paper, 2019). A progressive degenerative disorder of the central nervous system characterized by loss of dopamine producing neurons in the substantia nigra and the presence of Lewy bodies in the substantia nigra and locus coeruleus. "Whilst there are no candidate disorders for MRPL34, other diseases, such as Parkinson’s disease (previously linked to reduced mtDNA CN), are related to other mitochondrial ribosomal proteins." (PMID 30704525, 2019).
cancer (2 papers, 2018 to 2025). A tumor composed of atypical neoplastic, often pleomorphic cells that invade other tissues. "Further, MRPL34, a mitochondrial ribosomal protein that plays roles in apoptotic and survival pathways in infectious diseases, was associated with M. magneticum, a TAM being explored for its potential role in cancer therapy." (PMID 41417796, 2025).
infection (1 paper, 2025). The state of being infected such as from the introduction of a foreign agent such as serum, vaccine, antigenic substance or organism. "Associations with M. magneticum and mitochondrial genes like MRPL34 and MRPS34 point to potential microbiome involvement in the host metabolic and apoptotic pathways during early infection stages." (PMID 41417796, 2025).
mitochondrial disease (1 paper, 2010). "mRpL34 is a protein involved in ribosomal protein translation and encoded by a class of genes responsible for mitochondrial diseases that typically lead to muscle and brain disorders." (PMID 20463973, 2010). "Other mitochondrial diseases have been linked to mutations in genes encoding respiratory chain proteins and, more recently, nuclear genes like mRpL34, that are responsible for mitochondrial ribosomal translation." (PMID 20463973, 2010).
MRPL34 also shares sentences with these, for which no sentence is quoted: brain disorder (1 paper); breast carcinoma (1); infectious disease (1); ovarian carcinoma (1); tumour (1).